ADAMTS1 (ADAM metallopeptidase with thrombospondin type 1 motif 1)
Diseases named in the same sentence as ADAMTS1 in open-access papers (continued):
Sharing a sentence is not in itself a finding about the gene and the disease.
breast carcinoma (continued). "Thus, we hypothesized that ligand-activated PPARδ plays a central role in the tumorigenicity of human breast cancers, by modulating the expression of TSP-1 through its degrading protease ADAMTS1." (PMID 29212212, 2017). "Moreover ADAMTS1 and MMP1 play a role in bone metastasis of breast cancer cells." (PMID 29202741, 2017). "ADAMTS1 has an anti-angiogenic role, while the role of ADAMTS6 has not been defined but it is known to be dysregulated in breast carcinoma." (PMID 30546831, 2018). "The over-expressed CCNE1, CLGN, NEK2, PTTG1 and RAD51, and the under-expressed ADAMTS1, FOS, FOSB, IL6 and ZFP36 in tumor cells are examples of breast cancer genes without differential promoter methylation between normal and tumor samples." (PMID 25706888, 2015).
pancreatic cancer (18 papers, 2010 to 2025). "ADAMTS1 expression is elevated in metastatic breast cancer and pancreatic cancer, where its expression is associated with invasiveness and lymph node metastasis." (PMID 20840749, 2010). "It has been reported that the expression level of ADAMTS1 is downregulated in pancreatic cancer patients; conversely, tumors with high ADAMTS1 expression are more likely to metastasize to lymph nodes." (PMID 40878842, 2025). "In contrast, matched LN metastases of gastric tumors expressed significantly higher ADAMTS1 than did primary tumors and related high levels of ADAMTS1 in pancreatic tumors were also correlated with higher incidences of LN metastasis." (PMID 38263290, 2024). "The cfDNA methylation status of two pancreatic-cancer-associated genes, ADAMTS1 and BNC1, has been demonstrated to be highly sensitive and specific, enabling early pancreatic cancer diagnosis." (PMID 39200847, 2024). "ADAMTS1 shows high frequency promoter methylation in lung and pancreatic cancers; ADAMTS5 and ADAMTS1 also show high frequency methylation in colorectal cancer." (PMID 34603444, 2021). "Another study identified BNC1 and ADAMTS1 hypermethylation as potential biomarker to detect early‐stage pancreatic cancer, with sensitivities of 79% and 48% and specificities of 89% and 92%, respectively." (PMID 32243066, 2020). "The AUC for early stage, resectable pancreatic cancers was 0.91 (95% CI 0.85–0.95) for ADAMTS1, AUC 0.78 (95% CI 0.70–0.85) for BNC1 alone, while the AUC of the two-gene combination was 0.95 (95% CI 0.90–0.98)." (PMID 30953539, 2019). "Low expression of ADAMTS1 in pancreatic cancer tissue compared to normal pancreas tissue has previously been studied; however, large variability in the data resulted in the relationship being non-significant (p = 0.206)." (PMID 30004416, 2018). "In breast and pancreatic cancer, ADAMTS1 has been shown to promote metastasis by enhancing cellular migration and invasion." (PMID 20840749, 2010). "Yi and colleagues used new methylation-on-bead technology with quantitative MSP to specifically screen serum circulating free DNA (cfDNA) for promoter methylation changes in the BNC1 and ADAMTS1 loci—two genes that were verified to be hypermethylated in pancreatic cancer." (PMID 34968245, 2021). "ADAMTS1 is highly expressed in pancreatic cancer and ovarian cancer." (PMID 32884571, 2020). "However, more research is needed to determine the role of oleuropein and hydroxytyrosol on ADAMTS1 functions as well as the role of ADAMTS1 on pancreatic cells and pancreatic cancer disease progression." (PMID 30004416, 2018). "In breast and pancreatic cancer, the matrix metalloproteinase properties of a disintegrin and metalloprotease with a thrombospondin repeat (ADAMTS1), along with its anti-angiogenic role, have been shown to influence metastasis through the promotion of cellular migration and invasion." (PMID 20840749, 2010). "However, the specific role of ADAMTS1 in pancreatic cancer is yet to be determined." (PMID 30004416, 2018). "The methylation status of ADAMTS1 and BNC1 in cfDNA shows promise for detecting pancreatic cancer during the early stages when curative resection of the tumor is still possible." (PMID 30953539, 2019). "We have recently identified promoter DNA methylation of the genes ADAMTS1 and BNC1 as potential blood biomarkers of pancreas cancer." (PMID 30953539, 2019). "Our studies identified two biomarkers ADAMTS1 (A disintegrin and metalloproteinase with thrombospondin motifs 1) and BNC1 (zinc finger protein basonuclin-1) as highly sensitive markers for the early detection of pancreatic cancer in tissue." (PMID 30953539, 2019). "When considering the combination panel of both genes (ADAMTS1 and/or BNC1), the combined panel was positive in 100% (8/8) of stage I, 88.9% (8/9) of stage IIA, 100% (20/20) of stage IIB, and 100% (2/2) of stages III and IV pancreatic cancers." (PMID 30953539, 2019).
pancreatic cancer (continued). "Methylation of ADAMTS1 was found to be positive in cfDNA of 87.5% (7/8) patients with stage I cancer, 77.8% (7/9) of stage IIA, 90% (18/20) of stage IIB, and 100% (2/2) of stage III/IV pancreatic cancer patients." (PMID 30953539, 2019). "Four out of six pancreatic cancer cell lines also showed ADAMTS1 expression, in addition to both noncancerous and pancreatic cancer tissues." (PMID 24213506, 2012). "Surprisingly, in pancreatic cancer, although ADAMTS1 levels were much lower in comparison to noncancerous pancreatic tissue, patients with lymph node metastasis or severe retroperitoneal invasion exhibited higher levels of ADAMTS1 expression and poorer recovery rates." (PMID 24213506, 2012). "ADAMTS1 mRNA expression significantly lower in pancreatic cancer compared to noncancerous pancreas." (PMID 24213506, 2012).
prostate carcinoma (12 papers, 2010 to 2025). A carcinoma that arises from epithelial cells of the prostate gland. "In prostate cancer, ADAMTS1 plays intricate and complex roles linked to the ability of tumors to respond to the hormone androgen." (PMID 24213506, 2012). "On one hand, ADAMTS1 is lowered in prostate cancer and may be involved in early stages of prostate cancer development, with low levels of ADAMTS1 associated with high microvessel density and metastasis." (PMID 24213506, 2012). "This new data together with our results presented here, implies that loss of ADAMTS1 could be an important mediator of the progression into more aggressive prostate cancer." (PMID 20546609, 2010). "ADAMTS1 suppresses tumor growth in human fibrosarcoma and prostate cancer cells by regulating VEGF and fibroblast growth factor 2, thereby inhibiting angiogenesis." (PMID 40867252, 2025). "Some studies have also found that the expression of ADAMTS1 decreased in colorectal carcinoma, prostate carcinoma, and other tumors, but increased in cervical carcinoma." (PMID 36947712, 2023). "Of those that can cleave VCAN, ADAMTS-1 and -15 are the most highly expressed in prostate cancer cell lines, with ADAMTS-1 demonstrated to possess tumor suppressor activity in prostate cancer, and ADAMTS-15 expression shown to be androgen-dependent." (PMID 32354091, 2020). "Both EAF2 and ADAMTS1 mRNA expression levels were significantly reduced in prostate cancer tissues compared to normal adjacent tissue." (PMID 24260246, 2013). "Genes encoding secreted proteins ADAMTS1, IGFBP5 and WNT5A were significantly down-regulated in NCCIT cells co-cultured with CD90+ prostate cancer-associated fibroblasts compared to induction by normal prostate stromal cells." (PMID 24260246, 2013). "EAF2 and ADAMTS1 expression were also decreased significantly in human prostate cancer compared to normal adjacent tissues." (PMID 24260246, 2013). "ADAMTS1 expression was also markedly low in human prostate cancer cells and in patients with metastases from hormone refractory prostate tumors." (PMID 24213506, 2012). "A few of these (regions associated with ADAMTS1, SCARF2, and DSCR9) were tested further, and in combination, showed ~100% sensitivity and ~85% specificity for prostate cancer compared to matched adjacent benign tissues." (PMID 21669002, 2011). "Decreased expression of the angiogenesis inhibitor ADAMTS1 (ADAM metallopeptidase with thrombospondin type 1 motif, 1) has previously been reported during prostate cancer progression." (PMID 20546609, 2010). "Since ADAMTS1 is known as a potent inhibitor of angiogenesis in other systems and previously has been reported to decrease during prostate cancer progression, we investigated its effects on tumor blood vessels." (PMID 20546609, 2010). "Altogether, the results presented in this paper further support that ADAMTS1 is an important regulatory factor of tumor growth and angiogenesis during prostate cancer progression." (PMID 20546609, 2010). "In a previous study, we identified ADAMTS1 as a gene that was downregulated when the androgen-dependent human prostate cancer cell line LNCaP progressed into an androgen-independent subline, LNCaP-19." (PMID 20546609, 2010). "In the present study, we modified the expression of ADAMTS1 in an experimental model of prostate cancer to investigate the function of this protein." (PMID 20546609, 2010). "In this study, we identified several genes including the cytokines Il-6, Tgfb2, Cxcl1, and Ctgf, metallopeptidases Mmp13, Adamts1, Adamts4, and Adamts5, and transcription factors Junb, Fos, Stat3 and Cebpb that were up-regulated in osteoblasts as a result of prostate cancer–osteoblast interactions." (PMID 27600237, 2015). "To explore whether RPL31, HIST1H2BD, and ADAMTS1 expression levels were altered in clinical prostate cancer samples, we assessed the expression status of these genes based on the ONCOMINE microarray dataset." (PMID 25285958, 2014).
prostate carcinoma (continued). "Our results together with these previous findings suggest that ADAMTS1 may play a role in bicalutamide resistance and other tumorigenic changes in prostate cancer cells." (PMID 25285958, 2014). "ADAMTS1 expression is also decreased in human prostate cancer." (PMID 24260246, 2013). "ADAMTS1 was downregulated by shRNA technology in the human prostate cancer cell line LNCaP (androgen-dependent), originally expressing ADAMTS1, and was upregulated by transfection in its subline LNCaP-19 (androgen-independent), expressing low levels of ADAMTS1." (PMID 20546609, 2010). "This study was conducted to investigate the actual function of ADAMTS1 in prostate cancer." (PMID 20546609, 2010). "Furthermore, decreased expression of ADAMTS1 was found in tumor tissue from prostate cancer patients compared to benign prostate tissue, and low levels of ADAMTS1 were associated with increased MVD and metastasis in androgen-independent tumors." (PMID 20546609, 2010). "Furthermore, upregulation of ADAMTS1 by ETS transcription factor gene (ERG) has been shown to contribute to an invasive phenotype in prostate cancer." (PMID 20840749, 2010). "Moreover, ADAMTS-1 is also able to function as a versicanase, with evidence that it is reduced in prostate cancer, suggesting it may act in concert with ADAMTS-15." (PMID 32354091, 2020). "In order to further examine the potential correlation of EAF2 and ADAMTS1 in human prostate cancer, mRNA levels of EAF2 and ADAMTS1 were analyzed in laser capture microdissected human prostate tissue specimens." (PMID 24260246, 2013). "In addition, ADAMTS1 expression was reduced in prostate cancer in some datasets (data not shown)." (PMID 25285958, 2014).
atherosclerosis (11 papers, 2013 to 2025). A disease characterized by the build-up of fatty material and calcium deposition in the arterial wall resulting in partial or complete occlusion of the arterial lumen. "Indeed, transgenic overexpression of ADAMTS1 caused inflammatory cell infiltration into extracellular spaces and severe remodeling after carotid artery ligation in ApoE-deficient atherosclerosis model mice." (PMID 40362650, 2025). "This review aims to consolidate existing evidence on the multifaceted role of ADAMTS1 in cardiovascular remodeling, focusing on its dual functions across various cardiovascular diseases such as atherosclerosis, aortic aneurysms, and heart failure." (PMID 41440846, 2025). "The research indicates that miR-362-3p is integral to the pathogenesis of atherosclerosis by regulating ADAMTS1 expression." (PMID 40861271, 2025). "In another cellular study, miR-362-3p is shown to directly bind to and negatively regulate the expression of a disintegrin and metalloproteinase with thrombospondin motifs 1 (ADAMTS1), which suppresses VSMCs proliferation and migration in atherosclerosis." (PMID 40861271, 2025). "During the progression of atherosclerosis, ADAMTS1 primarily exerts pathological effects, specifically by promoting plaque vulnerability and driving adverse vascular remodeling." (PMID 41440846, 2025). "The deregulated miR-362-3p was involved in the regulation of vascular smooth muscle cell proliferation and migration in atherosclerosis according to downregulating ADAMTS1." (PMID 32178736, 2020). "ADAMTS-1 was already described to be enhanced in rat proximal tubules after I/R and also in atherosclerosis with macrophage invading the tissue." (PMID 30642356, 2019). "Inactivation of ADAMTS1 by HOCl, if this occurs in vivo, may result in a disturbance in aggrecan homeostasis, and accumulation during the development of atherosclerosis." (PMID 36829979, 2023). "ADAMTS4 and ADAMTS1 may be involved in atherosclerotic plaque formation and stability, as both have been found to be highly expressed in macrophage-rich areas of human atherosclerosis plaques." (PMID 35606349, 2022). "In conclusion, these findings suggest that ADAMTS-1 may play a detrimental role in the aetiology of atherosclerosis, whereas further studies are required to establish its involvement in the development of aortopathies." (PMID 33352066, 2020). "ADAMTS1 may contribute to atherosclerosis, possibly by enhancing cell proliferation and migration, whilst knockout of Adamts1 in mice resulted in either reduced or increased incidence and mortality of thoracic aortic aneurysms dependent on the specific model and/or mouse strain used." (PMID 36813235, 2023). "According to the literature, most ADAMTS (including the most proteolytically active ADAMTS-1 and ADAMTS-4) are responsible for PG degradation and, thus, are atherosclerosis development." (PMID 39859253, 2025). "Moreover, we decided on ADAMTS-1, which to our knowledge, no one has studied so far in the context of atherosclerosis." (PMID 39859253, 2025).
lung carcinoma (11 papers, 2006 to 2025). "For example, ADAMTS1 expression is upregulated in lung carcinoma and associated with EMT both in vitro and in vivo." (PMID 41211185, 2025). "The GSEA results suggested that decreased ADAMTS1 in lung cancer was associated with poor survival and cancer metastasis." (PMID 35625488, 2022). "MR analysis via the Wald ratio or IVW method revealed a causal relationship between ADAMTS1 or AMAMTS16 and the risk of lung cancer." (PMID 39551781, 2024). "Higher levels of ADAMTS1 (OR: 1.28, 95% CI: 1.14–1.41) and ADAMTS16 (OR: 1.1, 95% CI: 1.01--1.19) were genetically predicted to be associated with lung cancer." (PMID 39551781, 2024). "qRT-PCR was used to detect the expression of TGF-β in lung cancer cell line A549 after transfection of ADAMTS1." (PMID 36947712, 2023). "Epigenetic modulation of low ADAMTS1 expression through promoter hypermethylation has also been studied in prostate, colorectal, and lung cancers." (PMID 35625488, 2022). "The ADAMTS1-plasmid transfected A549 cells were injected into the nude mice to verify lung cancer metastasis." (PMID 35625488, 2022). "In this study, we found that ADAMTS1 influenced the infiltration of immune cells in the lung cancer microenvironment." (PMID 35625488, 2022). "This study used specimens from the in-house lung cancer cohort and public cohort to verify the roles of downregulated ADAMTS1, a protease remodeling extracellular matrix, to facilitate cancer promotion and progress." (PMID 35625488, 2022). "With the knockdown of ADAMTS1, A549 lung cancer cells exhibited more aggressive behaviors such as EMT and increased migration, resulting in cancer metastasis in a mouse model." (PMID 35625488, 2022). "Higher levels of this ADAMTS subtype have also been associated with pancreatic and hepatocellular cancer whereas ADAMTS-1 mRNA levels are unchanged in the onset and progression of kidney cancer and decreased in lung carcinomas." (PMID 21494557, 2011). "In this context, our finding of a significant decrease of ADAMTS-1 in lung cancer is of particular importance." (PMID 16495931, 2006). "Both ADAMTS1 and ADAMTS16, promote lung cancer metastasis in animal models: ADAMTS1 accelerates spontaneous pulmonary metastasis of Lewis lung carcinoma in C57BL/6 mice, while ADAMTS16 enhances pulmonary metastasis of A549 cells following tail vein injection in nude mice." (PMID 41465277, 2025). "Furthermore, ADAMTS-1 was reported to inhibit angiogenesis in lung cancer cells by regulating the PI3K/Akt-eNOS/VEGF axis." (PMID 39329961, 2024). "Our results showed that overexpression of ADAMTS1 could promote the proliferation, migration, and invasion of lung cancer cells." (PMID 36947712, 2023). "si-TGF-β or inhibition of TGF-β expression through the short peptide KTFR on ADAMTS1 protein could reverse the oncogenic effects of ADAMTS1 on lung cancer cells." (PMID 36947712, 2023). "Upregulation of ADAMTS1 may increase T cell immune infiltration and function of lung cancer, thereby improving the disease outcome of LUAD patients." (PMID 35625488, 2022). "Based on the clinical specimens, cell and animal study with the aid of the public databases, we concluded that downregulated expression of ADAMTS1 might promote tumor progression and metastasis and modify the tumor microenvironment in lung cancer." (PMID 35625488, 2022). "Similarly, seven out of eight patients in the lung cancer cohort from Oncomine also supported ADAMTS1 being reduced in lung tumor tissue." (PMID 35625488, 2022). "Additionally, GSEA analysis showed the enrichment of EMT and metastatic signaling pathways with low ADAMTS1 expression of lung cancer in the TCGA cohort." (PMID 35625488, 2022). "Furthermore, ADAMTS1 may be involved in the malignant behaviors of lung cancer cells by regulating the expression of TGF-β, suggesting that ADAMTS1 was involved in the regulation of NSCLC cells by positively regulating TGF-β." (PMID 36947712, 2023).
lung carcinoma (continued). "Collectively, these results suggest that ADAMTS1 promotes the activation of TGF-β through the KTFR sequence and promoting lung cancer cell migration, invasion and EMT." (PMID 36947712, 2023). "However, the role of ADAMTS1 downregulation in lung cancer remains unknown." (PMID 35625488, 2022). "Reports on prostate, colon and lung cancer have shown lower expression of ADAMTS1 in primary cancers compared to non-tumorigenic tissue." (PMID 30004416, 2018). "In addition to ADAMTS1, several ADAMTS members are found altered in lung cancer tissues." (PMID 36947712, 2023). "In addition, CancerSEA analysis, which was empowered to evaluate the functional assays of a selected gene, showed a strong correlation between ADAMTS1 and A2M, with phenotype changes contributing to cancer spreading, including EMT, metastasis, and quiescence in lung cancer." (PMID 35625488, 2022).